ALDH2 (aldehyde dehydrogenase 2 family member)
Diseases named in the same sentence as ALDH2 in open-access papers (continued):
Sharing a sentence is not in itself a finding about the gene and the disease.
heart failure (19 papers, 2012 to 2026). Inability of the heart to pump blood at an adequate rate to meet tissue metabolic requirements. "Elevated levels of 4HNE are associated with reduced ALDH2 activity, and animal models have shown that the E487K genetic mutation in ALDH2 can exacerbate characteristics of heart failure with preserved ejection fraction." (PMID 40429692, 2025). "Additional research has found that carriers of the ALDH2*2 variant have a heightened likelihood of heart failure with preserved ejection fraction due to increased inflammation, and those with moderate alcohol consumption have poorer left atrial function, increasing the risk of atrial fibrillation." (PMID 40564981, 2025). "ALDH2 deficiency contributes to endothelial cell damage, inflammatory responses, and mitochondrial dysfunction, making cardiac tissue more vulnerable to ischemic injury and increasing susceptibility to heart failure." (PMID 40564981, 2025). "Since the beneficial effects of α-LA in the pressure overload induced cardiac failure is ALDH2 dependent, the efficacy of α-LA might be limited in population with a G-to-A point mutation of the ALDH2 gene." (PMID 32732978, 2020). "Studies have shown that patients with the ALDH2*2 mutation are at increased risk of cardiovascular and metabolic disorders, including CAD, heart failure, and type 2 diabetes." (PMID 40564981, 2025). "As a highly efficient metabolic enzyme in mitochondria, increasing evidence supports an important role of ALDH2 in heart failure." (PMID 35645834, 2022). "ALDH2 was reported to attenuate cardiovascular diseases through the regulation of autophagy including heart failure, diabetic cardiomyopathy, and myocardial dysfunction." (PMID 35770049, 2022). "FUNDC1 mitophagy was found downregulated in pressure-overload induced heart failure, the effect of which was restored by α-LA treatment, in an ALDH2 dependent manner." (PMID 35645834, 2022). "This study demonstrated that AD-9308 treatment protected diabetic mice from heart failure through restoration of ALDH2 activity and reduction of the 4-HNE level in STZ-induced diabetic cardiomyopathy." (PMID 33805825, 2021). "We further used HSF1 transgene and knockout mice after TAC for 4 weeks and observed that HSF1 transgene mice recorded improved heart failure, which indicates that HSF1 probably plays its role in delaying the occurrence of heart failure via regulating ALDH2." (PMID 32626739, 2020). "The impact and related mechanisms of α-LA, a known ALDH2 activator, in pressure overload induced cardiac remodeling and heart failure are not fully understood." (PMID 32732978, 2020). "To examine the role of ALDH2 in the cardioprotective effect of HSF1 in attenuating heart failure, we used the adenovirus transfection method to establish the ALDH2 upregulation/downregulation model of HSF1 transgene mice." (PMID 32626739, 2020). "ALDH2 can ameliorate myocardial apoptosis from heart failure and delay the occurrence and development of heart failure." (PMID 32626739, 2020). "ALDH2, an enzyme involved in the activation of NO compounds, plays a role in the bioactivation of multiple drugs used for heart failure, such as glyceryl trinitrate and pentaerythritol tetranitrate." (PMID 22984478, 2012). "The indispensable role of ALDH2 in the pathogenesis of heart failure reveals that targeting ALDH2 might be a potential therapeutic option for heart failure and other cardiovascular diseases." (PMID 32732978, 2020). "However, using transgene technology to increase the expression of ALDH2 can contribute to antagonizing heart failure and decreasing heart function." (PMID 27547765, 2016). "In summary, our results suggest that α-LA could attenuate pressure overload induced cardiac injury in an ALDH2 dependent manner, clinical studies are warranted to verify if α-LA could be a potential useful therapeutic option to treat heart failure patients with pressure overload and with WT ALDH2." (PMID 32732978, 2020).
heart failure (continued). "Colocalisation with heart failure implicates 23 shared loci and bioinformatic analysis prioritises genes including HSPB7, CAMK2D, ALDH2, ENG, and YWHAE." (PMID 41760662, 2026). "We first established the pressure overload-induced heart failure model of mice by transverse aortic constriction (TAC) and discovered that, in the forming period of heart failure, changes of HSF1 and ALDH2 expression recorded the consistent trend." (PMID 32626739, 2020). "And when ALDH2 was upregulated/downregulated, the role of HSF1 in delaying the occurrence of heart failure strengthened/weakened." (PMID 32626739, 2020). "But when heart failure occurred four weeks after TAC, HSF1 transgene mice recorded better heart function, and at the same time, the expression of ALDH2 mRNA and protein recorded increases." (PMID 32626739, 2020). "When HSF1 was upregulated/downregulated to delay/promote the occurrence of heart failure, PKC and ALDH2 also showed increased/decreased expression." (PMID 32626739, 2020). "In summary, through animal and cell experiments, we explored a novel mechanism for the occurrence and development of heart failure and demonstrated that HSF1 is the upstream regulating factor for ALDH2, and one of the mediators is PKC." (PMID 32626739, 2020). "Four weeks after TAC, when the expression of ALDH2 protein was downregulated, the effect of HSF1 in delaying heart failure weakened, and when ALDH2 was upregulated, the record was the contrary." (PMID 32626739, 2020). "Through animal and cell experiments, we demonstrated the effect of HSF1 in promoting pressure-stimulated myocardial hypertrophy and further ameliorating heart failure by upregulating ALDH2 via PKC, providing a novel theoretical basis for exploring treatment approaches of heart failure." (PMID 32626739, 2020). "We discovered that, in the forming period of heart failure, HSF1 and ALDH2 recorded the consistent trend in terms of expression of their mRNA and protein, indicating that there exists a correlation between HSF1 and ALDH2." (PMID 32626739, 2020). "Additionally, when ALDH2 in the heart of the HSF1 transgene mice was downregulated, the role of HSF1 in delaying the occurrence of heart failure weakened, and when ALDH2 was upregulated, the result was the contrary, when the expression of HSF1 increased, that of PKC also increased." (PMID 32626739, 2020). "By upregulating expression of ALDH2 via mitochondrial import of PKCε while upregulating HSP90, HSF1 can play the protective role in response to myocardial hypertrophy injury resulting from pressure stimulation and further delay the occurrence and development of heart failure of mice." (PMID 32626739, 2020). "HSF1 and ALDH2 are potential endogenous cardioprotective factors, and there are already lots of evidences for their cardioprotective effect, but it is not yet reported whether HSF1 can regulate ALDH2 to delay the occurrence of heart failure." (PMID 32626739, 2020). "Evidences abound that HSF1 and ALDH2 are of cardioprotective effect, yet there is still no report on whether HSF1 can regulate ALDH2 to delay the occurrence of heart failure." (PMID 32626739, 2020).
ischemia (19 papers, 2012 to 2025). A hypoperfusion of the BLOOD through an organ or tissue caused by a PATHOLOGIC CONSTRICTION or obstruction of its BLOOD VESSELS, or an absence of BLOOD CIRCULATION. "The underlying mechanisms for the protective effects of ALDH2 against ischemia are multiple, such as decreasing toxic aldehydes accumulation, enhancing autophagy via AMPK-and Akt/mTOR signal, promoting apoptosis by MAPK-ERK1/2-JNK-p38 pathway and modulating ER stress." (PMID 25629048, 2015). "In 2008, we showed direct correlation between ALDH2 activity and infarct size in a model of ischemia and reperfusion using Langendorff isolated heart model, using inhibitors and activators of ALDH2 the R2 correlation with infarct." (PMID 37693644, 2023). "Alda-1, a potent activator of ALDH2, protects against oxidative stress in models of ischemia by bolstering the activity of ALDH2." (PMID 33597876, 2020). "As a special activator of ALDH2, Alda‐1 was firstly discovered by Chen et al42 in 2008 and was proved to play a beneficial role in attenuating ischemia‐induced heart dysfunction." (PMID 29799157, 2018). "ALDH2 was found to attenuate ethanol exposure-induced myocardial dysfunction, and activation of ALDH2 led to cardiac protection against ischemia and reperfusion injury." (PMID 27829984, 2016). "Aldh2 catabolizes toxic aldehydes in the liver after alcohol consumption, in the heart after ischemia, and in dopamine metabolism." (PMID 22840776, 2012). "Here, we show a protective effect of low-dose systemic sodium nitrite in prevention of IR injury to the human vascular endothelium, when administered 24 h before the insult, and additionally in some participants (depending upon ALDH2 genotype) when administered during ischemia." (PMID 28280793, 2017). "Recently, ALDH2 was identified as a target for oxidative modification during glyceryl trinitrate tolerance; and ALDH2 activity was correlated inversely with cardiac infarct size in rat hearts subjected to ischemia and reperfusion ex vivo." (PMID 27829984, 2016). "Interestingly, N-(1,3-benzodioxole-5-ylmethyl)-2,6-dichlorobenzamide (Alda-1), an aldehyde dehydrogenase 2 (ALDH2) agonist that increases the activity of mitochondrial ALDH2, inhibits myocardial damage caused by 4-HNE after ischemia." (PMID 26083658, 2015). "Interestingly, in support of a role for ALDH-2, human volunteers with a Glu504Lys polymorphism in ALDH-2 were found to be resistant to RIC protection against ischemia-induced endothelial dysfunction." (PMID 25449895, 2015). "However, Alda-1 (16 μg/g) given 2 hr prior to ischemia significantly elevated myocardium ALDH2 activity and inhibited 4-HNE-protein adduct formation in aged hearts (both P<0.05)." (PMID 24040162, 2013). "Consistently, overexpression of ALDH2 gene in mice decreases 4-HNE levels elevated by ischemia and reperfusion and significantly alleviates ischemia/reperfusion injury and hypoxia/reoxygenation-induced cardiomyocyte contractile dysfunction." (PMID 26491656, 2015).
lung adenocarcinoma (19 papers, 2020 to 2025). A carcinoma that arises from the lung and is characterized by the presence of malignant glandular epithelial cells. "ALDH2 deficiency or the ALDH2rs671 mutation can increase sensitivity to platinum-based chemotherapy in lung adenocarcinoma by increasing ferroptosis in lung adenocarcinoma tissues." (PMID 40968356, 2025). "Conversely, the downregulation of ALDH2 is associated with poor prognosis in lung adenocarcinoma (LUAD)." (PMID 40088196, 2025). "Another study also showed that ALDH2 repression is associated with a poor prognosis in patients with lung adenocarcinoma." (PMID 34025411, 2021). "In lung adenocarcinoma, down-regulation of ALDH2 expression leads to the accumulation of acetaldehyde, which promotes the proliferation and migration abilities of lung adenocarcinoma cells." (PMID 38378847, 2024). "Accumulating evidence suggests that ALDH2 dysfuction contributes to human diseases such as cancers, and ALDH2 is suppressed in human lung adenocarcinoma." (PMID 35494074, 2022). "Silencing of the ALDH2 locus by DNA methylation has been reported as a mechanism of ALDH2 downregulation in lung adenocarcinoma." (PMID 34454516, 2021). "ALDH2 suppression also promotes proliferation and stemness of lung adenocarcinoma cells both in vitro and in vivo." (PMID 33201835, 2020). "When Lung adenocarcinoma cells treated with ALDH2 agonist, they have suppressed proliferation, stemness and migration features." (PMID 33201835, 2020). "Paradoxically, enhancing the activity of ALDH2 by N-(1,3-benzodioxol-5-ylmethyl)-2,6-dichlorobenzamide, commonly known as Alda-1 inhibited the cancer stemness, proliferation and migration, leading to minimization of DNA damage in lung adenocarcinoma cells." (PMID 34940794, 2022). "Lower levels of 4-HNE were found to be more sensitive to ferroptosis in lung adenocarcinoma, so we hypothesized that decreasing 4-HNE via ALDH2 would cause tumor cells to be more sensitive to ferroptosis in PCa." (PMID 36144737, 2022). "ALDH2 is suppressed in human lung adenocarcinoma, its repression leads to ACE accumulation in lung adenocarcinoma cells and induces DNA damage and metastatic features." (PMID 33201835, 2020).
type 2 diabetes (19 papers, 2013 to 2025). "The rs671 polymorphism in ALDH2 was pinpointed as a risk factor for the occurrence of death from cardio-cerebrovascular complications in patients with type 2 diabetes and has recently been characterized as a novel regulator of cholesterol biosynthesis." (PMID 38732608, 2024). "Among them, the ALDH2 Glu504Lys mutation that affects 560 million East Asians or nearly 8% of global population is associated with body mass index, type 2 diabetes, and serum lipids in large meta-analyses of genome-wide association studies." (PMID 37749090, 2023). "Since the ALDH2 Glu504Lys mutation is reported to be associated to type 2 diabetes in genome-wide association studies in East-Asians9, we further examined glucose homeostasis in mice." (PMID 37749090, 2023). "ALDH2*2 is associated with maternal inheritance of type-2 diabetes and diabetic complications including diabetic cardiac dysfunction." (PMID 29677191, 2018). "The ALDH2*2 mutation increases acetaldehyde accumulation, which has been associated with elevated HbA1c levels, insulin resistance, and obesity in patients with type 2 diabetes, thereby implicating the variant in broader metabolic abnormalities." (PMID 40564981, 2025). "utilized MRI to assess visceral fat area (VFA) and subcutaneous fat area (SFA), demonstrating that the ALDH2 rs671 G allele was specifically associated with increased visceral fat accumulation, which is a well-established risk factor for insulin resistance and type 2 diabetes." (PMID 40046877, 2025). "ALDH2*1/*2 may increase the risk of noninsulin-dependent diabetes mellitus (NIDDM)." (PMID 34439969, 2021). "As expected, HFD-induced type-2 diabetes in ALDH2*2 mice increased hyperglycemia compared to chow-fed ALDH2*2 mice." (PMID 36142350, 2022). "We fed a high-fat diet to ALDH2*2 mice, which have intrinsically low ALDH2 activity, to induce type-2 diabetes." (PMID 36142350, 2022). "After 4 months, we found a significant increases in the heart rate after exercise in both C57BL/6 and ALDH2*2 mice free of diabetes and ALDH2*2 mice with 4 months of type-2 diabetes." (PMID 29677191, 2018). "Multiple logistic regression analysis for diabetic complications according to ALDH2 activity (ALDH2 *1/*1 active vs. *1/*2 or *2/*2 inactive) and drinking status in Japanese patients with type 2 diabetes." (PMID 26599441, 2015). "Metabolic parameters according to ALDH2 activity (ALDH2 *1/*1 active vs. *1/*2 or *2/*2 inactive) and drinking status in Japanese patients with type 2 diabetes." (PMID 26599441, 2015). "Blood pressure and diabetic complications according to ALDH2 activity (ALDH2 *1/*1 active vs. *1/*2 or *2/*2 inactive) and drinking status in Japanese patients with type 2 diabetes." (PMID 26599441, 2015). "Clinical characteristics according to ALDH2 activity (ALDH2 *1/*1 active vs. *1/*2 or *2/*2 inactive) and drinking status in Japanese patients with type 2 diabetes." (PMID 26599441, 2015). "Genetic variants in or near the CDKAL1, KLF9, GP2, ALDH2, and ITIH4 genes are associated with obesity and genetic variants in or near the GDAP1, PTF1A, SIX3, ALDH2, and PAX4 genes are specifically associated with type 2 diabetes in East Asians." (PMID 37749090, 2023). "Our ALDH2*2 E487K knock-in mutant mice mimic East Asians with the ALDH2*2 E487K mutation and we demonstrated that this ALDH2*2 E487K knock-in mutant mice with HFD-fed type-2 diabetes recapitulated major characteristics of HFpEF." (PMID 36142350, 2022). "The objectives of this study are to determine whether ALDH2*2 mice with type-2 diabetes exhibit the HFpEF phenotype and to evaluate the capability of our exercise echo stress test methodology in detecting this cardiac functional anomaly." (PMID 29677191, 2018).
type 2 diabetes (continued). "The non-CHD indications of clinically used drugs included dyslipidemias (PPARA), type 2 diabetes (PPARG and NDUFA13), autoimmune diseases (TNF), neoplasms (RAF1 and PSMA5), circulatory disorders (ABCA1, PLG, ITGB3, and F2), and alcohol-dependency (ALDH2)." (PMID 34675202, 2021). "In this circumstance, the ALDH2 activator Alda-1 still potentiated the insulin secretion of MIN6 cells in both low and high glucose concentrations, suggesting a potential for the treatment of type 2 diabetes subjects." (PMID 34680107, 2021).
Hepatic steatosis (18 papers, 2015 to 2025). Steatosis is a term used to denote lipid accumulation within hepatocytes. "In this study, the association between ADH1B/ALDH2 gene polymorphism and serum metabolic factors, body statures, and hepatic steatosis/fibrosis status was evaluated in patients with NAFLD." (PMID 37240928, 2023). "Consistently, PARP1 inhibition rescued ALDH2 deficiency–induced fatty liver and elevated HDL-C in AKO mice." (PMID 35393951, 2022). "The WD-induced fatty liver due to ALDH2 deficiency was significantly prevented with PARP1 inhibition." (PMID 35393951, 2022). "Aldh2 KI and HE mice also had significantly higher hepatic triglycerides contents and more severe hepatic steatosis than the WT mice on HFHSD (0.32 ± 0.05 vs, 0.21 ± 0.03 vs. 0.19 ± 0.03 mg/mg liver tissue, P-for-trend = 0.034) at the age of 24 weeks." (PMID 37749090, 2023). "Our study also showed that the Aldh2 KI mice had more severe hepatic steatosis than the WT mice when fed on HFHSD, which can be reversed by AD-9308 treatment." (PMID 37749090, 2023). "Experiments in ALDH2 transgenic mice demonstrated that ALDH2 mitigates alcohol-induced liver steatosis and inflammation through the regulation of autophagy." (PMID 37189787, 2023). "AD-9308 treatment reduced the extent of hepatic steatosis and the levels of hepatic triglycerides contents in both Aldh2 KI and WT mice in a dose-dependent manner." (PMID 37749090, 2023). "ALDH2 dysfunction will lead to several diseases, such as cancer, alcoholic fatty liver, and cardiovascular diseases." (PMID 31842750, 2019). "ALDH2 activators such as Alda-1 may mitigate liver damage in mice by improving aldehyde elimination and reversing liver steatosis and apoptosis." (PMID 41567634, 2025). "However, studies on the association between hepatic steatosis, fibrosis and the influence of combining ADH1B and ALDH2 allele in patients with NAFLD remain scarce." (PMID 37240928, 2023). "ALDH2 could ameliorate chronic alcohol intake-induced hepatic steatosis and inflammation through the regulation of autophagy." (PMID 35237626, 2022). "Additionally, chronic alcohol intake was reported to suppress hepatic autophagy and to promote liver steatosis as well as inflammation, which can be reversed by mitochondrial aldehyde dehydrogenase (ALDH2), a detoxification enzyme of ethanol metabolite acetaldehyde." (PMID 30642133, 2019). "ALDH2 may inhibit metastasis in HCC cells by regulating the AMPK signaling pathway and also ameliorate chronic alcohol-induced hepatic steatosis and inflammation through up-regulation of the autophagy pathway." (PMID 35237626, 2022). "All these data suggest that ALDH2 downregulated ABCA1 expression and decreased cholesterol efflux from LKO liver tissues through attenuating poly(ADP-ribosyl)ation of LXRα, which manifested as lower levels of HDL in the circulation but increased hepatic steatosis in ALKO compared with LKO mice." (PMID 35393951, 2022).